SIPA1 (signal-induced proliferation-associated 1)
Diseases named in the same sentence as SIPA1 in open-access papers (continued):
Sharing a sentence is not in itself a finding about the gene and the disease.
cancer (16 papers, 2012 to 2025). A tumor composed of atypical neoplastic, often pleomorphic cells that invade other tissues. "Because normal epithelial cells in the breast duct hardly activate Sipa1, the transcription of Sipa1 via promoter hypomethylation seems to be an aberrant event associated with cancer progression." (PMID 32193333, 2020). "Based on these findings, it is likely that a high level of SIPA1 expression is correlated with mesenchymal features of cancer cells, whereas a low level of SIPA1 expression is associated with epithelial features of cancer cells." (PMID 32193333, 2020). "Taken together, it is most likely that the methylation status of Sipa1 is inexorably linked to the regulation of SIPA1 expression in cancer cells." (PMID 32193333, 2020). "Moreover, particular hypomethylation of many genes, including signal-induced proliferation-associated 1 (SIPA1), has also been connected to the development of cancer." (PMID 39858015, 2025). "The cancer-associated role of SIPA1 differs in human malignant tumors." (PMID 35431649, 2022). "Subsequently, we identified five genetic variants in known cancer-related genes (located within SIPA1, ADCY7 and ARNT2) that could be associated with cancer mortality residuals corrected for confounding factors." (PMID 32661568, 2020). "It is, therefore, imperative to verify that SIPA1 serves as a TF and regulates cancer progression in TNBC, which would allow us to further understand the onset and progression of TNBC and to develop a novel clinical means to treat TNBC." (PMID 37500797, 2023). "Previous studies suggested a role of SIPA1 in the proliferation and metastasis of a variety of cancers." (PMID 37500797, 2023). "In terms of the mechanism, SIPA1 in cancer cells modulated the key protein myosin-9 in EVs and promoted macrophage infiltration via EVs." (PMID 35453742, 2022). "Accumulating evidence indicates that SIPA1 is highly expressed in various solid tumors and that its expression is correlated with metastasis and poor prognosis in many types of cancers." (PMID 35096814, 2021). "The transcriptional expression level of SIPA1 was found to be higher in cancer than adjacent normal tissue or normal tissue in the Peking clinical cohort." (PMID 33917539, 2021). "In colorectal cancer (CRC) cell lines HT115 and CaCO-2, knockdown of SIPA1 increased the invasion, adhesion, and migration potential of cancer cells compared to the control group, while the ability to proliferate was decreased." (PMID 33917539, 2021). "We found that CpG methylation status was negatively correlated with SIPA1 expression in human tissues as well as cancer cell lines." (PMID 32193333, 2020). "We next compared the expression patterns of VIM (vimentin) and CDH1 (E-cadherin) with those of Sipa1 using qRT-PCR in the cancer cell lines studied herein." (PMID 32193333, 2020). "The present study, however, demonstrated that hypomethylation of the Sipa1 promoter-proximal elements resulted in a high level of Sipa1 transcription and SIPA1 protein expression in several cancer cells." (PMID 32193333, 2020). "Moreover, SIPA1 increased macrophage infiltration and led to cancer metastasis via myosin-9-enriched EVs." (PMID 35453742, 2022). "Subsequently, SIPA1 was found to be important in the development of various cancers and metastases." (PMID 33917539, 2021). "SIPA1 may have a key role in the invasion and metastasis of cancer via various signaling molecules and pathways." (PMID 32699531, 2020). "In addition, we demonstrate in the present study that various cancer cell lines express SIPA1 to different degrees." (PMID 32193333, 2020). "Taken together, hypomethylation of Sipa1 promoter-proximal elements by treating MCF7 cells with 5-Aza-CdR upregulated the expression of SIPA1 and vimentin, suppressed E-cadherin expression, and promoted the cancer cell migration, which might lead to EMT." (PMID 32193333, 2020).
cancer (continued). "In this study, we identified human Sipa1 promoter-proximal elements that contained a CpG island and demonstrated that the methylation status of the CpG island was inversely correlated with SIPA1 protein expression in cancer cells." (PMID 32193333, 2020). "In some cancerous tissues such as the breast, prostate and colon, a markedly high level of SIPA1 is expressed, compared with that in the surrounding normal tissues, that may be responsible for cancer metastasis." (PMID 32193333, 2020). "Based on the present data, the inhibitors could facilitate the transcription of certain oncogenes such as Sipa1, which might have influence on the fate of cancer cells." (PMID 32193333, 2020). "Furthermore, we made comparisons between the methylation status of the Sipa1 promoter region in human tissues and cancer cell lines from the GEO whole-genome bisulfite sequencing dataset, and Sipa1 transcription levels in human tissues and cancer cell lines from Human Protein Atlas." (PMID 32193333, 2020). "SIPA1 has been shown to be involved in MET signaling and may contribute to tight junction (TJ) function and cancer metastasis." (PMID 33917539, 2021).
SIPA1 also shares sentences with these, for which no sentence is quoted: adenocarcinoma (1 paper); anemia (1); bladder cancer (1); breast cancer in situ (1); cervical cancer (1); chronic myelogenous leukemia (1); colon cancer (1); colorectal cancer (1); endometrial adenocarcinoma (1); gastric cancer (1); metastatic tumor (1); oral squamous cell carcinoma (1); Splenomegaly (1); T-cell leukemia (1).